ALK (ALK receptor tyrosine kinase)
Diseases named in the same sentence as ALK in open-access papers (continued):
Sharing a sentence is not in itself a finding about the gene and the disease.
inflammatory myofibroblastic tumor (continued). "The diagnosis of anaplastic lymphoma kinase (ALK)-negative inflammatory myofibroblastic tumors (IMT) remains challenging because of their morphological resemblance with spindle cell sarcoma with myofibroblastic characteristics." (PMID 32195970, 2020). "Negative staining for STAT6, ALK and HHV8 effectively excluded solitary fibrous tumors, inflammatory myofibroblastic tumors and Kaposi's sarcoma, respectively." (PMID 40900681, 2025). "Histopathology confirmed an inflammatory myofibroblastic tumor (IMT; anaplastic lymphoma kinase [ALK]-negative, mouse double minute 2 homolog-positive)." (PMID 40917711, 2025). "DOG-1, ALK and Desmin were negative, which ruled out the close differentials like GIST, Inflammatory myofibroblastic tumor and leiomyoma and further supporting the diagnosis of myopericytoma." (PMID 40043410, 2025). "In a patient with an inflammatory myofibroblastic tumor, conventional fluorescence in situ hybridization (FISH) analysis showed negative ALK rearrangement, but a TPM4-ALK translocation was detected by targeted sequencing." (PMID 31747416, 2019). "In our case, it is easily to rule out diagnoses of inflammatory myofibroblastic tumor (IMT), aggressive fibromatosis, nodular fasciitis (NF), solitary fibrous tumor (SFT), since it is negative for ALK (5A4), β-catenin, SMA, Desmin, and CD34." (PMID 31311568, 2019). "Diagnosis can be difficult because imaging and biopsy may not distinguish it from an inflammatory pseudotumor (IPT) or spindle cell sarcoma, particularly in ALK‐negative tumours with broader pathological variability." (PMID 41368177, 2025). "Based on the morphological, immunohistochemical, molecular findings and the good response to receptor tyrosine kinases inhibitors, the final diagnosis of the inflammatory myofibroblastic tumor with a previously undescribed ROS1 fusion is made, although ALK rearrangement is negative." (PMID 37735390, 2023). "In this case, anaplastic lymphoma kinase (ALK) and immunoglobulin G4 (IgG4) negativity ruled out inflammatory myofibroblastic tumor (IMT) and IgG4-related disease." (PMID 40964556, 2025).
melanoma (176 papers, 2011 to 2026). A malignant, usually aggressive tumor composed of atypical, neoplastic melanocytes. "In silico mutational modeling and docking results have been applied as a tool to predict potential utility in predicting drug responses in EGFR-mutant NSCLC,28,29BRAF-mutant NSCLC,30BRAF-mutant melanoma, and ALK-mutated NSCLC." (PMID 39500140, 2024). "Since this study, several others have confirmed the presence of other types of ALK mutations in melanoma." (PMID 28895885, 2017). "ALK missense mutations have been reported in a systematic review of next-generation sequencing data from melanoma samples." (PMID 28895885, 2017). "It is possible that different mutation types are involved in different subsets of melanoma, with ALK translocations involved in acral melanoma and the ALKATI isoform in nodular subtypes." (PMID 28895885, 2017). "ALK expression in melanoma resulted from a novel transcript variant, known as ALKATI." (PMID 39530091, 2024). "In addition to SNVs, recent studies have discovered that the expression of ALK is associated with the efficacy of immunotherapy in melanoma." (PMID 39025927, 2024). "However, it has been associated with ALK-fused spitzoid neoplasms, melanoma or liver neuroendocrine tumors, among others." (PMID 35884384, 2022). "This MCL-1 dependence was driven by a significant downregulation of the sensitizer NOXA, which frees MCL-1 after treatment with ALK-TKIs to block therapy-induced apoptosis, as previously demonstrated in other solid tumors such as melanoma and rhabdomyosarcoma." (PMID 40113795, 2025). "Patients with brain metastases from melanoma, breast cancer, certain genotypes of non-small cell lung cancer (NSCLC; e.g., EGFR-activating mutations, ALK translocations), and renal cell carcinoma benefit most from a multidisciplinary approach." (PMID 41296115, 2025). "In the 6-week-old infant with melanoma and a second case occurring at 10 months, a ZEB2:ALK fusion were found in associated benign tumors, up to 10 months before malignancy was detected." (PMID 39755235, 2025). "This cancer involved a ZEB2:ALK fusion gene, as well as amplifications of parts of chromosomes 6p and 11q that are frequently seen in melanoma in addition to other chromosomal aberrations." (PMID 39755235, 2025). "Previous research demonstrated a high prevalence of ALK expression in melanoma patients with wildtype BRAF or NRAS34,35." (PMID 39025927, 2024). "On the contrary, ALK expression had a favorable impact on the prognosis of NRAS wild type melanomas." (PMID 39025927, 2024). "Eleven % of melanoma tissues present a truncated ALK transcript resulting in a smaller protein, which was shown to be oncogenic." (PMID 36831417, 2023). "Crizotinib is a multi-targeted tyrosine kinase inhibitor, targeting ALK, c-Met, and ROS1, and FDA approved for the treatment of non-small cell lung cancer (NSCLC) patients with ALK rearranged mutations and melanoma patients." (PMID 38144528, 2023). "For example, in patients with Her2-positive breast cancer BMs, those with ALK-rearranged or EGFR-mutated NSCLC BMs, and for BRAF V600 E mutated melanoma BMs, targeted therapies with significant intracranial activity are available." (PMID 36605448, 2022). "In melanoma, recent clinical trials have shown that the pan-Trk inhibitor entrectinib is has a therapeutic impact in Trk-fusion melanoma, but the mechanism is uncertain as entrectinib can also inhibit other signaling molecules, such as ROS-1 or ALK." (PMID 35457078, 2022). "In various cancers, including glioblastoma, melanoma, breast, lung, and prostate, tyrosine kinases are the most representative of these kinases, e.g., ALK, ROS1, RET, and FGFR." (PMID 35054873, 2022). "Genes from the RTK/PI3K pathway, including PTEN, PIK3R1 in glioma, and ALK, PIK3C2G, ERBB4 in melanoma, showed lower mutation rates in AYAs, reiterating our earlier observation on recurrent genes." (PMID 36433963, 2022).
melanoma (continued). "For example, targeted therapies have established intracranial activity in patients with Her2-positive breast cancer BM, ALK-rearranged or EGFR-mutated NSCLC BM and for BRAF V600E mutated melanoma BM." (PMID 36605448, 2022). "BRAF V600E -positivity was less frequent in Spitzoid melanomas compared to the other melanoma types (35.1% vs. 68.4%), while all five tumours positive for ALK were Spitzoid melanomas." (PMID 35037531, 2022). "Non-metabolism-related proteins (BRCA1, phosphorylase B kinase regulatory subunit: PHKA1, tyrosine-protein kinase receptor: ALK and rho-associated protein kinase: ROCK1) correlated to melanoma development differed among all groups." (PMID 34199079, 2021). "In this context, Janostiak and coworkers showed that both B-RAF kinase inhibitor (Vemurafenib) plus anaplastic lymphoma kinase (ALK) inhibitor (Ceritinib) resistant A375 melanoma cells isolated from xenograft mice are sensitive to AT-101 treatment." (PMID 33523262, 2021). "The PI3K/AKT signaling pathway, downstream of ALK, was required for ALK activity, and the ALK inhibitor ceritinib abrogated the BRAFi resistance in melanoma cells." (PMID 34063141, 2021). "Combined treatment with vemurafenib and ALK inhibitors efficiently decreases tumor burden in mice bearing ALK-positive melanoma tumors." (PMID 33920605, 2021). "Targeted therapies, however, can be very effective against established BM from different entities, such as BRAF and MEK inhibitors in melanoma, EGFR and ALK inhibitors in lung adenocarcinoma, and immune checkpoint inhibitors in melanoma and lung cancer." (PMID 32918638, 2020). "Recently, it was also demonstrated that ALK in the exosomes secreted by BRAF inhibitor-resistant melanoma cells transferred drug resistance through activation of the MAPK signaling pathway in recipient cells." (PMID 32379831, 2020). "It has been reported that resistant melanoma cells can activate the MAPK pathway in sensitive melanoma cells through an EV-mediated truncated ALK transfer." (PMID 33080788, 2020). "In some cases, the large epithelioid cytology resembled that reported in NTRK-fusion melanomas, as well as in some Spitz tumors with ALK translocation." (PMID 32123303, 2020). "Recently, another set of three constitutively activated ALK truncated isoforms of 58–61 kDa was discovered in a subset of human melanomas (11% of cases)." (PMID 30813562, 2019). "In the wake of the discovery of the novel ALK isoform (ALKATI) identified in melanoma patients, we next characterised ALKRES protein by performing 5′-rapid amplification of cDNA ends (5′-RACE) followed by Sanger sequencing." (PMID 30290811, 2018). "Next, seven melanoma cell lines and normal melanocytes were screened for the presence of ALK transcripts using primers in the kinase domain of ALK but none except A375X1 were positive for ALK." (PMID 30290811, 2018). "In melanoma cell lines, FHIT expression was associated with chemoresistance to the ALK inhibitor TAE684 (ρ = 0.621, padj = 0.0326, n = 38, Ntests = 26,610)." (PMID 29642934, 2018). "As ALK has recently been described to be present in an oncogenic form in melanoma patients, we focused our attention on ALK." (PMID 30290811, 2018). "In particular, we assessed if ALK mRNA transcripts in NB cells retain evidence of intron 19 (I19), since ALK transcripts retaining portions of intron 19 were detected in subsets of melanoma and other tumors." (PMID 29535836, 2018). "To assess the effect of BRAF and ALK inhibition in vivo, we tested vemurafenib, ceritinib and the combination of both in mice harbouring A375-X1-induced melanoma tumours." (PMID 30290811, 2018). "Efficacy of molecular-targeted medicine for cancers with driver oncogenes, such as HER-2 amplification in breast cancer, EGFR mutation and ALK-rearrangement in NSCLC, and BRAF mutation in malignant melanoma, is found to be very high." (PMID 30443294, 2018).
melanoma (continued). "The possibility of ALK expression in melanoma was first characterized in acral melanomas among patients in Southern China." (PMID 28895885, 2017). "In fact, discrepant results between ALK transcript and protein expression have been demonstrated in Calas (melanoma) and NCI-H69 (small cell lung carcinoma) cells." (PMID 28193280, 2017). "The new ALK isoform is specifically expressed in around 11% of melanomas that further show a specific response to the ALK inhibitor." (PMID 28471386, 2017). "While limited again by sample size, they report that ALK-positive melanomas were primarily nodular, and composed predominantly of amelanotic epithelioid or mixed spindle and epithelioid cells." (PMID 28895885, 2017). "Many RAS pathway inhibitors, including RAF inhibitors and MEK inhibitors, have been developed and show superior effects in the treatment of malignant melanoma, Her2-positive breast cancer, and anaplastic lymphoma kinase (ALK)-positive NSCLC." (PMID 26630652, 2015). "Additionally, advanced salvage options—such as repeat SRS and systemic therapies effective for intracranial and extracranial disease (e.g., melanoma and NSCLC with EGFR mutations or ALK translocations)—challenge the routine use of WBRT." (PMID 41296115, 2025). "Instances of such onco-exaptation events include the elevated expression of CSF1R and IRF5 in Hodgkin’s lymphoma, the ectopic expression of CALB1 (encoding calbindin) in squamous lung cancer, and the creation of an oncogenic form of ALK (anaplastic lymphoma kinase) in melanoma." (PMID 40336011, 2025). "In practice, systemic-first strategies are reasonable for asymptomatic, small-volume brain metastases from EGFR/ALK-driven NSCLC or BRAF-mutant melanoma, initiating CNS-active systemic therapy and deferring focal radiotherapy with MRI surveillance every 6–8 weeks." (PMID 41296115, 2025). "In a small phase II study, alectinib has shown activity in melanoma, papillary urothelial carcinoma and colon adenocarcinoma with ALK rearrangements, but not in any cases of solid organ tumours with ALK mutations or amplification." (PMID 39188081, 2024). "In addition to the co-occurrence between SNVs and ALK expression, our study also demonstrated that ALK expression alone can negatively impact the prognosis of melanoma patients with both CMM and ALM." (PMID 39025927, 2024). "Therefore, compared to IHC, RNAseq can more accurately reflect the true proportion of ALK expression-positive patients in melanoma." (PMID 39025927, 2024). "Moreover, we found that ALK expression serves as a prognostic indicator in melanoma patients receiving immunotherapy." (PMID 39025927, 2024). "ALK expression has been identified in metastatic and primary melanomas." (PMID 39530091, 2024). "This outcome aligns with a previous xenograft study utilizing the A375P melanoma cell line, which also lacked ALK rearrangements or mutations." (PMID 38399413, 2024). "Surprisingly, we found high numbers of ALK rearrangements in melanoma (n = 4) for the first time." (PMID 36612279, 2022). "Efficacy and limitations of targeted therapies for LM from EGFR-mutant and ALK-rearranged NSCLC, HER2-positive breast cancer and BRAF-mutated melanomas are reported, including the use of intrathecal administration or modification of traditional cytotoxic compounds." (PMID 34207653, 2021). "ALK was identified as another kinase conferring BRAFi resistance in melanomas." (PMID 34063141, 2021). "Similarly, a novel truncated but functional form of the ALK (anaplastic lymphoma kinase) protein (ALKRES) can be incorporated into exosomes secreted from melanoma cells and transported to cells of the tumor microenvironment." (PMID 33920605, 2021). "As ALK fusions have recently been shown to be involved in resistance to BRAF inhibitors in melanoma, combinatorial therapies combining ALK inhibitors with other targeted therapies might lead to some therapeutic benefit in a subset of CRC patients." (PMID 32019056, 2020).
melanoma (continued). "Additionally, in 2015, Wiesner and colleagues identified in 11% of melanoma tissues a truncated ALK transcript starting from intron 19 and resulting in a smaller protein, which was shown to be oncogenic." (PMID 30290811, 2018). "Many mechanisms of melanoma drug resistance have recently been put forward but so far, ALK has not been implicated." (PMID 30290811, 2018). "Even within this small cohort, the data suggest that pharmacological inhibition of ALK combined with BRAF inhibitors might represent an interesting therapeutic opportunity for a subset of melanoma patients." (PMID 30290811, 2018). "In a subset of melanoma, portions of I19 also was also detected in the ALK transcripts; importantly, these I19-containing ALK transcripts were found to be responsible for the aberrant expression of ALK in these tumors, as the I19 portions contain the transcription initiation sites." (PMID 29535836, 2018). "To determine how many patients could potentially benefit from dual inhibition of BRAF and ALK, we analysed the TCGA database focusing on melanoma patients." (PMID 30290811, 2018). "Finally, the combination of BRAF and ALK inhibitor treatments of mice bearing ALK-positive melanoma tumours dramatically reduced tumour volumes, making ALK an exciting clinical target in melanoma patients." (PMID 30290811, 2018). "Instead, further research identifying the specific characteristics of ALK-positive spitzoid lesions, and their distinct characteristics, may help elucidate distinction of spitzoid lesions suspicious for melanoma or other malignant neoplasms." (PMID 28895885, 2017). "Altogether, these data suggest an emerging role for ALK in the pathogenesis of melanoma." (PMID 28895885, 2017). "Further study will be required to characterize a more accurate frequency of ALK-positive melanomas, and whether they present with a distinct morphologic phenotype." (PMID 28895885, 2017). "There are multiple examples of oncogenic mutations that predict benefit from FDA-approved targeted therapies (CML/imatinib, melanoma/BRAFi, lung/EGFR and ALK inhibitors, breast/HER2 inhibitors), and other mutations that predict resistance (RAS mutations and EGFR inhibitors)." (PMID 27776519, 2016). "In comparison to other targeted agents such v-raf murine sarcoma viral oncogene homolog B1 (BRAF) inhibitors in melanoma or crizotinib in anaplastic lymphoma receptor tyrosine kinase (ALK) translocated tumors, the number of objective responses to PI3K inhibitors is less dramatic." (PMID 23232172, 2012). "In this regard, our findings suggest that expression of CR-1 might significantly enhance the metastatic potential of melanoma cells through the activation of the Nodal/ALK/Smad pathway." (PMID 21863025, 2011). "As for triple-wild melanoma, analysis with larger gene panels is worthwhile, as it has a higher probability to find targets for tumor-agnostic targeted therapies in this tumor type, such as RET, NTRK (neurotrophic tyrosine receptor kinase), ALK (anaplastic lymphoma kinase) or even IDH1 mutations." (PMID 40361349, 2025). "Recently, a novel isoform of ALK (ALKATI) (a truncated isoform, driven from an alternative transcription initiation (ATI) site in intron 19, encoding only the intracellular domain of ALK) has been described as being expressed in ~11% of melanomas and sporadically in other human cancers." (PMID 31366041, 2019). "Next, we asked whether the dependence of A375X1 melanoma cells on ALK could be exploited to overcome BRAF inhibitor resistance and we treated the cells with three different ALK inhibitors (Crizotinib, Ceritinib and ASP3026) alone or in combination with PLX4032." (PMID 30290811, 2018). "In addition, a new ALK transcript consisting of a fragment of intron 19 followed by exons 20–29 that resulted from an alternative transcription initiation was recently identified in 11% of melanoma patients." (PMID 30290811, 2018).